CDKN2A (cyclin dependent kinase inhibitor 2A)
Diseases named in the same sentence as CDKN2A in open-access papers (continued):
Sharing a sentence is not in itself a finding about the gene and the disease.
astrocytomas (continued). "The remaining 5 cases in which loss of CDKN2A was detected comprised one ganglioglioma, one pediatric-type IDH-wildtype infiltrating astrocytoma, one meningioma, one neuroepithelial tumor not otherwise specified (NOS), and one ‘malignant neoplasm, NOS’." (PMID 36397144, 2022). "Univariable and multivariable Cox regression analysis for survival in IDH-mut lower grade astrocytomas (1p19q-noncodel) and oligodendrogliomas (1p19q-codel) without known CDKN2A/B homozygous deletion, n=157." (PMID 35083156, 2021). "For IDH-mut astrocytomas, the presence of CDKN2A/B homozygous deletion now classifies the tumor as a WHO grade 4 astrocytoma, even in the absence of histopathological features of necrosis and microvascular proliferation." (PMID 35083156, 2021). "Concomitant CDKN2A and CDKN2B HDs could be detected in patients with glioblastoma multiform cancer, astrocytoma, and gliosarcoma." (PMID 33980169, 2021). "We found in IDH-wt cohort that the cluster with high proportion of endothelial cells and B-cells prominently showed a greater number of samples with CDKN2A/B deletion and similarly in IDH-mut astrocytomas we found that in cluster 2 significant number of samples presented CDKN2A/B deletion." (PMID 34496929, 2021). "While our data show a similar poor prognosis of CDKN2A deletion in grade 4 IDHm astrocytomas, these findings do not extend to grade 3 tumors." (PMID 33081848, 2020). "Moreover, the CDKN2A homozygous deletion in GBM and astrocytoma entail either partial or complete codeletion of the type I IFN cluster in more than 50% of these tumors." (PMID 32516884, 2020). "The histologic spectrum of the astrocytomas that arise as part of this syndrome is not well described, nor are the additional genetic alterations that drive these astrocytomas apart from the germline CDKN2A inactivation." (PMID 28699883, 2017). "CDKN2A/B was a survival predictor in WHO grade 2 astrocytoma but not in WHO grade 3." (PMID 42109834, 2026). "This classification suggests that, in theory, there could be three subgroups of IDHm astrocytoma WHO grade 4; those exhibiting only molecular WHO grade 4 criteria (CDKN2A/B deletion), those with only morphological WHO grade 4 criteria and those presenting with combined criteria." (PMID 40392514, 2025). "Of the nine cases of grade 4 astrocytoma, IDH-mutant, four were classified based on pathological features (microvascular proliferation and necrosis), four were classified based on molecular features (CDKN2A/B HD), and one was classified based on both pathological and molecular feature." (PMID 39636550, 2025). "Astrocytoma, IDH-mutant with homozygous deletion of CDKN2A and/or CDKN2B (CDKN2A/B-HD) carries a poor prognosis, and CDKN2A/B-HD tumors are graded as “astrocytoma, IDH-mutant, CNS grade 4,” even in the absence of histological features of necrosis or microvascular proliferation." (PMID 39636550, 2025). "However, the absence of T2-FLAIR mismatch sign does not completely predict astrocytoma with CDKN2A-HD." (PMID 39117984, 2024). "The T2-FLAIR mismatch sign was negative for all cases of astrocytoma with CDKN2A-HD." (PMID 39117984, 2024). "There is growing evidence suggesting the importance of CDKN2A deletion as a prognostic marker for adverse clinical outcomes in several CNS tumors, including supratentorial ependymoma with ZFTA fusion, high-grade meningioma, anaplastic IDH-mutant astrocytoma, and oligodendroglioma." (PMID 39457569, 2024). "However, it remains to be elucidated the prognostic value of methylation-based lower-grade astrocytomas with or without CDKN2A/B deletions concerning survival outcomes of the patients." (PMID 36739454, 2023).
astrocytomas (continued). "Due to an insufficient number of IDH-mutant astrocytomas in our cohort, we could not reliably assess the prognostic impact of CDKN2A homozygous deletion in this grade 4 histomolecular entity." (PMID 36900302, 2023). "Not all studies supported the use of CDKN2A/B in IDH-mutant astrocytomas." (PMID 37504251, 2023). "Indeed, the presence of a CDKN2A homozygous deletion would now classify an IDH-mutant astrocytoma as WHO grade 4, even in the absence of microvascular proliferation or necrosis." (PMID 36900302, 2023). "Importantly, the presence of CDKN2A HD (with pathologists’ p16 score of 1%) upgraded one IDH-mutant astrocytoma without microvascular proliferation or palisading necrosis to grade 4." (PMID 37138345, 2023). "The presence of a CDKN2A/B homozygous deletion isindicative of a high-grade astrocytoma, even in the absence of high-gradehistological findings, such as microvascular proliferation and necrosis.Low-grade IDH-mutant astrocytomas can undergo late transformation to high grade." (PMID 37564083, 2023). "This elevated copy number burden is found in IDH-mutant astrocytomas with poor clinical outcomes and with additional established poor prognostic molecular features, such as CDKN2A and CDK4, but is also found in cases where no other features suggestive of higher molecular grade are present." (PMID 35978439, 2022). "In addition, CDKN2A and CDKN2B deletions indicate poor prognosis in IDH-mutant astrocytoma." (PMID 34210109, 2021). "However, CDKN2A deletion, in IDH-mutant astrocytomas, is a marker of the highest malignancy grade." (PMID 34638714, 2021). "Similarly, the astrocytoma IDH-mutant grade 4, as identified through CDKN2A/B homozygous deletions, could preferably have been excluded from our cohort." (PMID 34621684, 2021). "Compared to prior studies, the lack of prognostic significance of CDKN2A homozygous deletion by FISH in grade 2–3 IDH-mutant astrocytomas may reflect differences in cohort populations or technical differences between testing modalities." (PMID 33081848, 2020). "In the present study, we subclassify 135 astrocytomas (67 IDH-wildtype and 68 IDH-mutant) from The Cancer Genome Atlas dataset (TCGA) on the basis of grade, IDH-status, and the previously established prognostic factors, CDK4 amplification and CDKN2A/B deletion, within the IDH-mutant groups." (PMID 31177992, 2019). "The purpose of this study was to correlate conventional MRI features with homozygous deletion of CDKN2A and/or CDKN2B, type of IDH mutation (IDH1-R132H or non-canonical) and overall survival in a cohort of histological grade 2–3 IDH-mutant and 1p/19q-non-codeleted astrocytomas." (PMID 37316586, 2023). "Based on this hypothesis, we examined the multi-gene proliferation score (MGPS) between Astrocytoma samples with and without CDKN2A/B homozygous deletion, and found Astrocytoma samples with CDKN2A/B homozygous deletion showed elevated MGPSs, suggesting their fast proliferation feature." (PMID 36720864, 2023). "Additionally, in the Consortium to Inform Molecular and Practical Approaches to CNS Tumor Taxonomy—Not Official WHO (cIMPACT‐NOW) update 5, IDH‐mutant astrocytomas with CDKN2A/B homozygous deletion were classified into WHO grade 4 regardless of pathological findings." (PMID 33838014, 2021). "However, the histologic features of the astrocytomas that arise as part of this syndrome are not well described, nor are the somatic genetic alterations that drive these astrocytomas in addition to the germline CDKN2A inactivation." (PMID 28699883, 2017).
astrocytomas (continued). "In patients with non-enhancing astrocytoma, IDH-mutant, the T2-FLAIR mismatch sign is a potential imaging biomarker for the CDKN2A-intact subtype." (PMID 39117984, 2024). "According to the recent change of IDH-mutant astrocytoma grading in the 2021 WHO Classification of CNS tumors, tumors containing CDKN2A/B HD are accepted as grade 4 even if they do not contain MVP and/or necrosis." (PMID 38109891, 2024). "Among non-enhancing astrocytoma, IDH-mutant, the T2-FLAIR-mismatch sign is a potential imaging biomarker for CDKN2A-intact subtype." (PMID 39117984, 2024). "In this study, we explored the association between radiological characteristics of non-enhancing astrocytoma, IDH-mutant to the CDKN2A/B status." (PMID 39117984, 2024). "In case of the presence of CDKN2A and CDKN2B homozygous deletion (CDKN2A/B-HD), the tumor is graded as “astrocytoma, IDH-mutant, grade 4,” even in the absence of histological features such as necrosis or microvascular proliferation." (PMID 39117984, 2024). "They reported CDKN2A/B as a predictor of survival in morphologically grade 4 IDH-astrocytomas but not for grade 2 and 3 IDH-mutant astrocytomas." (PMID 37504251, 2023). "An important refinement in WHO 2021 is the addition of homozygous deletion of CDKN2A and/or CDKN2B to the grading of IDH-mutant astrocytomas, related to the negative survival implications." (PMID 37316586, 2023). "In our cohort, 3 out of 20 IDH-mutant astrocytomas and none out of 8 IDH-mutant oligodendrogliomas contained CDKN2A HD, overall consistent with prior reported frequencies." (PMID 37138345, 2023). "CDKN2A/B homozygous deletion in IDH-mutant astrocytomas has been shown to be a negative prognostic marker, and they should be diagnosed as astrocytoma IDH-mutant, CNS WHO grade 4 despite lack of microvascular proliferation or necrosis." (PMID 35879477, 2022). "According to this update, IDH-mutant astrocytoma (WHO grade IV), with CDKN2A/B locus homozygous deletion as molecular marker, previously classified as IDH-mutant GB, is now classified as “astrocytoma, IDH-mutant, WHO grade 4 and no longer as glioblastoma”." (PMID 34210109, 2021). "Based on these findings, according to the change in the grading of IDH-mutant astrocytomas in the 2021 WHO CNS tumors classification, tumors containing CDKN2A/CDKN2B HD are classified as grade 4 even if they do not contain microvascular proliferation and/or necrosis." (PMID 38109891, 2024). "Besides CDKN2A/B homozygous deletion (HD), there are no molecular markers that currently aid grading of IDH-mutant astrocytomas." (PMID 39382765, 2024). "None of the astrocytoma, IDH-mutant with CDKN2A-HD showed T2-FLAIR mismatch sign." (PMID 39117984, 2024). "The initial tumor of Case 4 may have been a lower-grade astrocytoma, not a GBM, at initial diagnosis, and it may have subsequently harbored CDKN2A/B homozygous deletions at recurrence 10 months after the first surgery." (PMID 36646712, 2023). "IDH-mutant astrocytomas with either CDK4 amplifications or CDKN2A deletions had significantly shorter survival (median PFS of 32 months; median OS of 36 months) compared to IDH-mutant astrocytomas without these alterations (median PFS of 95 months, p = 0.02; median OS of >172 months, p = 0.02)." (PMID 32640746, 2020).
cervical carcinoma (154 papers, 2004 to 2026). A carcinoma arising from either the exocervical squamous epithelium or the endocervical glandular epithelium. "High MCM2 expression has been correlated with high-risk HPV and p16/CDKN2A expression in cervical cancer samples." (PMID 31653153, 2019). "Moreover, CDKN2A promoter hypermethylation was associated with increased cancer cell migration and tumor invasiveness in laryngeal squamous cell carcinoma, and cervical cancer." (PMID 37626750, 2023). "In conclusion, NCAM1 and CDKN2A are two promising candidates to distinguish whether women are at high risk of developing cervical cancer and in need of frequent follow-up." (PMID 35008799, 2021). "Additional DEGs that were overexpressed in cluster 8 included several known canonical cervical cancer oncogenes – CDKN2A, SERPINB3, TP63, and KRT5." (PMID 41362277, 2026). "Luan Y., Zhang W., Xie J., Mao J. CDKN2A inhibits cell proliferationand invasion in cervical cancer through LDHA-mediated AKT/mTOR pathway." (PMID 40584241, 2025). "The transcription level of the CCL20 and CDKN2A genes becomes increased at the stage of neoplastic epithelial changes and stays so in cervical cancer." (PMID 38946889, 2024). "Based on the significant interactions of CDKN2A with transcription factors, signaling molecules, and miRNAs, this gene has been proposed as a biomarker for cervical cancer prognosis." (PMID 36765810, 2023). "A large number of studies have shown that CDKN2A is involved in poor prognosis in a variety of cancers, including hepatocellular carcinoma, cervical cancer, ovarian cancer and EC." (PMID 37723477, 2023). "Another contradictory finding was reported in an epigenetics study, in which the cervical cancer group showed significantly higher CDKN2A methylation than the control group, suggesting a low CDKN2A expression level in cervical cancer." (PMID 36765810, 2023). "In cervical tissue, the expression of CDKN2A is typically low, but higher expression (6-fold to 342-fold change) was reported in cervical cancer tissue in four of the selected studies in this systematic review." (PMID 36765810, 2023). "In cervical cancer, Hsa-mir-125b-5p expression was downregulated, and CDKN2A expression was upregulated, suggesting that hsa-miR-125a-5p-CDKN2A is a possible ceRNA network." (PMID 36531222, 2022). "A previous study revealed that miR-125a-5p/CDKN2A regulatory axis exerts a vital role in prognostic value in cervical cancer." (PMID 35937995, 2022). "There has been knowledge stating that hypermethylation of the CDKN2A gene can induce erosion of CDKN2A expression in many malignancies, involving hepatocellular carcinoma, cervical cancer, and non-small cell lung cancer." (PMID 33896386, 2021). "Recent studies conducted on cervical cancer suggested that patients who possess the CDKN2A methylation gene, as well as the drop in CDKN2A expression, suffered from a decreased OS rate." (PMID 34405225, 2021). "There are few researches have reported CDKN2A in cervical cancer tissues was negatively correlated with serosal invasion." (PMID 34405225, 2021). "Suppression of CDKN2A gene expression generally occurs by aberrant methylation of its promoter, and it also plays a crucial role during neoplastic progression in cervical cancer." (PMID 32025240, 2020). "Up-regulation of CDKN2A, also known as p16, in the early stage of cervical cancer is an indication of the host response in inactivating pRb gene and releasing the E2F family." (PMID 31653153, 2019).
cervical carcinoma (continued). "CDKN2A expression is a well-established marker for distinguishing HPV+ versus HPV− cervical cancers." (PMID 31796060, 2019). "Hypermethylation of the CDKN2A gene promoter is a frequent epigenetic change in younger patients with cervical carcinoma and implies a significant epigenetic role in tumor development in this age group." (PMID 29850477, 2018). "Loss of RB1 function, which is a well known phenomenon in cervical cancer leads to expression of Cyclin D1, over-expression/amplification of CDK4, and/or loss of the CDKN1B, CDKN2A and CDKN2B." (PMID 26701206, 2016). "This suggests the existence of other HPV-independent mechanisms that may affect CDKN2A overexpression, which has been confirmed in cervical cancer and cancers of the oral cavity and pharynx." (PMID 39590385, 2024). "CDKN2A is negatively correlated with serosal invasion in the cervical cancer tissue." (PMID 36891559, 2023). "Thus, due to the significantly promising role of CDKN2A in cervical cancer, further studies are crucial to address this conflicting finding." (PMID 36765810, 2023). "In cervical cancer, HPV E7 protein inactivates Rb, causing the overexpression of CDKN2A." (PMID 35740635, 2022). "The association between CDKN2A expression and HPV infection in oral and cervical cancer demonstrated that HPV acts via the oncoprotein E7, which can bind the Rb protein, resulting in the inhibition of the formation of the Rb complex with E2F family of transcription factors (for example E2F2)." (PMID 36551770, 2022). "The imbalance of CDKN2A, IL1R2, and RFC4 could promote the proliferation of cancer cells, which is closely related to the progress of cervical cancer, and might be a potential diagnostic marker and therapeutic drug targets." (PMID 33833775, 2021). "Acquired CDKN2A inactivation (gene deletion or hypermethylation resulting in decreased expression) at time of progression has been reported in studies of paired tumor analyses of other malignancies, including lymphoma, cervical cancer, and prostate cancer." (PMID 33153497, 2020). "Several studies suggested CDKN2A is a potential biomarker in cervical cancer." (PMID 31319555, 2019). "Taken together, our analysis of over 350 HPV+ head and neck or cervical carcinomas in comparison with over 450 HPV- cancers from their respective anatomical sites demonstrates that HPV consistently activates expression of both the CDKN2A and CDKN2B loci in these cancers." (PMID 29069809, 2017). "Cervical cancers express high levels of CDKN2A probably by a feedback mechanism." (PMID 21447152, 2011). "However, at the same time, another study of the CDKN2Aexpression in cervical cancer cell lines showed that it wasreduced; moreover, the authors concluded that CDKN2A inhibitscell proliferation and invasion in cervical cancer throughthe lactate dehydrogenase-mediated ACT-mTOR pathway." (PMID 40584241, 2025). "The level of CDKN2A mRNA expression was 4.7 times higher in HSIL (p = 0.014) and by 6.6 times (p = 0.001) higher in cervical cancer groups compared with chronic cervicitis." (PMID 35736434, 2022). "E7 via E2F also upregulates cyclin-dependent kinase inhibitor 2A (p16INK4A, or CDKN2A) expression, which acts as a prognostic biomarker for cervical cancer." (PMID 34680286, 2021). "During the progression of cervical cancer, from normal cervical tissues to CIN 1, 2 and 3, the up‐regulated genes we confirmed were SYCP2, NEFH, CDKN2A and KRT17." (PMID 33624385, 2021).